STAT2 (signal transducer and activator of transcription 2)
Diseases named in the same sentence as STAT2 in open-access papers (continued):
Sharing a sentence is not in itself a finding about the gene and the disease.
ZIKV infection (continued). "While there are major species differences, subtle evolutionary differences can also have large effects, as seen between human and mouse STAT2 in ZIKV infection." (PMID 39480108, 2024). "Proposed mechanisms to explain the low IFN induced by ZIKV infections include proteasomal degradation of the STAT2 activator and modulation of the biogenesis of peroxisomes, the signaling platforms during the IFN response." (PMID 37227282, 2023). "Further studies are required to test the protective role of palmitoleate against human ZIKV infection and in animal models such as using humanized STAT2 knock-in mice." (PMID 36615782, 2022). "On the other hand, NS5 expression causes IFN-regulated proteasome degradation of the transcriptional activator STAT2, which also reflects the importance of STAT2 during ZIKV infection." (PMID 35880081, 2022). "Recently, ZIKV infection to humanized STAT2 knockin mice during pregnancy showed increased placental and fetal brain infection." (PMID 36615782, 2022). "Mechanistically, we found that ZIKV infection triggered degradation of ubiquitinated STAT2 and host short-lived proteins while didn't affect the proteasome activity per se." (PMID 34340648, 2021). "To do this, we utilized ZIKV-infected pregnant Stat2-/- mice, a model we have previously employed to evaluate the enhancement of ZIKV infection in the presence of DENV antibodies." (PMID 34220838, 2021). "In line with this, the introduction of human STAT2 into the mouse STAT2 locus produced an immunocompetent mouse model for ZIKV infection." (PMID 34834923, 2021). "Other small animal models including hamsters, humanized STAT2 mice, and more recently the treeshrew, have been used in ZIKV infection studies." (PMID 34451435, 2021). "Taken together, these data indicate that ZIKV infection accelerated the proteasomal degradation of host ubiquitinated proteins, including STAT2." (PMID 34340648, 2021). "In line with previous reports, we found that exogenous murine STAT2 was refractory to ZIKV infection-induced degradation, which is probably due to the failure of NS5 recognition of murine STAT2." (PMID 34340648, 2021). "Several recent studies have reported that ZIKV infection was enhanced in the presence of convalescent plasma derived from DENV-infected patients in vitro, and passive transfer of anti-DENV immune sera exacerbated ZIKV infection in STAT2-/- knockout mice." (PMID 34170962, 2021). "Mechanistically, ZIKV infection accelerated the turnover of ubiquitinated host proteins and STAT2, probably by interrupting host de novo protein synthesis." (PMID 34340648, 2021). "It is possible that at high MOIs, ZIKV infection generates a high dosage of antagonists other than NS5 to suppress host de novo protein synthesis to ablate STAT2 signalling." (PMID 34340648, 2021). "We propose that ZIKV infection induces STAT2 ablation, probably through both the suppression of host de novo protein synthesis and the reported NS5-mediated degradation." (PMID 34340648, 2021). "Recent studies reported that ZIKV infection antagonizes type I IFN signaling by targeting STAT2 for proteasomal degradation." (PMID 33979266, 2021). "For example, immunocompetent mice are rather resistant to ZIKV infection because ZIKV NS5 is unable to degrade the antiviral molecule STAT2 in mice." (PMID 32628667, 2020). "Since both the Asian and African lineage Zika viruses induced cytokine gene expression in human DCs and also weakly in macrophages, we analyzed the level of phosphorylation of IRF3 and STAT2 in response to ZIKV infection." (PMID 31673117, 2019). "In summary, we first demonstrated ZIKV infection and immunotherapy in a new rodent animal model, the STAT2 KO hamsters." (PMID 30678320, 2019). "We first characterized the kinetics of viremia, the development of neutralizing antibodies, and the presence of virus in STAT2 KO hamsters following ZIKV infection." (PMID 30678320, 2019).
ZIKV infection (continued). "In the present study, we evaluated the anti-ZIKV human polyclonal antibodies (SAB-155) produced from TcB both as therapeutic and prophylactic treatments for ZIKV infection in STAT2 KO hamsters." (PMID 30678320, 2019). "Before the reduction in STAT2 activation, the expression of viral proteins was observed, suggesting that in primary human DCs ZIKV infection is leading to down-regulation of STAT signaling." (PMID 31673117, 2019). "Surprisingly, we observed IRF3 and STAT2 degradation in macrophages at early times of ZIKV infection." (PMID 31673117, 2019). "ZIKV infection induced strong upregulation of genes associated with IFN signaling such as IFNα, IFNβ, STAT1, and STAT2." (PMID 30781519, 2019). "We recently generated an immunocompetent model of ZIKV infection by introducing human STAT2 into the mouse Stat2 locus (hSTAT2 KI), which allows ZIKV to antagonize innate immune responses in mice." (PMID 30655513, 2019). "It was of interest that the degradation of IRF3 and STAT2 in macrophages took place at early hours of ZIKV infection, clearly before viral protein expression occurred." (PMID 31673117, 2019). "We next decided to study the role of STAT2 in the intracellular transcriptional response after ZIKV infection." (PMID 30453684, 2018). "Earlier work suggested that ZIKV NS5 targets STAT2 for degradation 19, 28 and that ZIKV infection blocks STAT1 phosphorylation." (PMID 29572905, 2018). "Recent studies have described the cellular innate immune response against ZIKV infection, specifically, the role of Toll-like receptors, as well as specific molecules involved in this response such as STAT2." (PMID 30453684, 2018). "The only exception to this trend was found for CXCL10 in placenta cells, which was upregulated after STAT2 knockdown; however, this upregulation decreased somewhat after ZIKV infection." (PMID 30453684, 2018). "Specifically, we studied the role of TLR7, TLR8, and STAT2 during ZIKV infection, since they are key molecules in the cellular antiviral and IFN-mediated responses." (PMID 30453684, 2018). "Following up on these observations we now demonstrate that ZIKV challenge in Stat2-/- mice results in ZIKV infection and spread to CNS, gonads and other vital organs, with manifestation of neurological symptoms." (PMID 28278235, 2017). "Taken together, Stat2-/- mice support ZIKV infection, with virus spread to CNS, gonads, spleen and liver." (PMID 28278235, 2017). "In terms of mortality all Stat2-/- and Ifnar1-/- mice succumbed to African ZIKV infections between day 6 to 8, with Stat2-/- mice displaying slightly higher early mortality as compared to Ifnar1-/- mice." (PMID 28278235, 2017). "However, to our knowledge, there have not been yet identified any ubiquitinating enzymes contributing to STAT2 degradation during ZIKV infection." (PMID 39773572, 2025). "However, STAT2 translocation, phosphorylation and total protein levels were more potently reduced by ZIKV infection compared to STAT1." (PMID 36897927, 2023). "Taken together, these results indicate that ZIKV infection reduces the protein levels of STAT2." (PMID 34340648, 2021). "A previous study reported that passive transfer of plasma from DENV immune patients into STAT2-/- mice enhanced ZIKV infection, and this led us to ask whether plasma anti-DENV IgG was responsible for disease enhancement." (PMID 34170962, 2021). "We show that purified DENV-specific IgG derived from three DENV-experienced human donors did not enhance ZIKV infection in susceptible STAT2-/- mice." (PMID 34170962, 2021). "However, host immune responses are weakened due to the degradation of STAT1 and STAT2 transcription factors that initiate the transcription of ISGs by NS2A during ZIKV infection." (PMID 34745057, 2021). "ZIKV infection has been reported to reduce STAT2 expression." (PMID 34340648, 2021). "As ZIKV infection induces degradation of STAT2 in a proteasome-dependent manner, we examined whether ZIKV NS5 triggers proteasomal degradation." (PMID 34340648, 2021).
ZIKV infection (continued). "To characterize the activity of neutralizing antibodies, the kinetics of viremia and viral presence in the testis of STAT2 KO hamsters following ZIKV infection, we infected three age-matched (6 weeks of age) male hamsters via the s.c route with PRVABC69 (~70 pfu) ZIKV." (PMID 30678320, 2019). "In fact, in most cases, we observed up-regulation of STAT2 protein during ZIKV infection." (PMID 28152048, 2017). "ZIKV NS5 has been observed to induce the proteasomal degradation of the interferon regulated transcriptional transactivator STAT2 in human cells but not mouse cells, and Stat2-null mice are highly susceptible to ZIKV infection." (PMID 29099873, 2017). "It will be interesting to test ZIKV infection of Stat2-/- as well as Stat2-/+ heterozygous mice in pregnancy models to see whether they can simulate the transplacental infection and neuroteratogenic properties of ZIKV." (PMID 28278235, 2017). "This knowledge led us to hypothesize that STAT2 could be critical for preventing ZIKV infection in animal models." (PMID 28278235, 2017). "We also examined whether ZIKV infection induced degradation of ubiquitinated STAT2." (PMID 34340648, 2021). "Furthermore, because ZIKV, as well as several other flaviviruses, exerts its infectivity in humans through targeting human STAT2 protein to inactivate human type I interferon responses, infection of STAT2 KO hamsters by ZIKV would mimic the innate immune responses in humans upon ZIKV infection." (PMID 30678320, 2019). "These hSTAT2-KI mice, which have human STAT2 replacing mouse STAT2, developed an intact IFN immunocompetent model of ZIKV infection and pathogenesis after peripheral inoculation." (PMID 40855992, 2025). "A major described mechanism involves STAT2 ubiquitination and proteasomal degradation by the NS5 protein, previously observed in DENV and ZIKV infections." (PMID 41477009, 2025). "During human ZIKV infection, the viral NS5 protein inhibits STAT2, thereby suppressing the type I IFN response to ZIKV, allowing for viral replication and dissemination." (PMID 40824033, 2025). "Molecules involved in type I IFN signaling are also increased by ZIKV infection, such as STAT1, DDX60L, DDX60, DDX58, STAT2, and IRF7." (PMID 36142200, 2022). "MAPK1 dysregulation induces chorio-retinal atrophy and optic nerve abnormalities in ZIKV infections and STAT1/2 is involved in antiviral responses; in addition, ZIKV NS5 protein-mediated STAT2 degradation modulates type I and III interferon responses." (PMID 36680137, 2022). "In the present study, ZIKV infection was shown to suppress type I IFN-mediated response and inhibited phosphorylation of STAT1 and STAT2 in moDCs, which is in line with previous findings." (PMID 33979266, 2021). "ZIKV infection impairs type I and III IFN signaling and suppresses the induction of downstream interferon-stimulated genes (ISGs) through virus-mediated STAT2 degradation." (PMID 33979266, 2021). "Recent studies have shown that ZIKV can interfere with interferon-induced responses: ZIKV infection inhibits STAT1 and STAT2 phosphorylation, and especially ZIKV NS5 protein inhibits STAT1 phosphorylation and induces the proteasomal degradation of STAT2." (PMID 31690057, 2019). "In contrast to DENV NS5, ZIKV infection was able to induce endogenous STAT2 degradation even in UBR4–/– cells, suggesting a unique mechanism of STAT2 inhibition by ZIKV NS5." (PMID 31652496, 2019). "In A549 cells and human DCs, ZIKV infection diminished the pools of endogenous phosphorylated STAT1 and STAT2 (p-STAT1/2), at residues Tyr-701 and Tyr-689, respectively, in the presence and absence of exogenous IFN treatment." (PMID 31652496, 2019). "Additionally, macrophages have been found to be vulnerable to ZIKV infection, although viral replication is limited due to the virus’ inability to counteract STAT1/STAT2 phosphorylation and the antiviral interferon response." (PMID 39057782, 2024).
ZIKV infection (continued). "As WT mice strongly resist ZIKV infection in the periphery due to an inability of ZIKV to antagonize murine STAT2 signaling, we used a mouse line harboring a homozygous replacement of the murine Stat2 gene with human STAT2 (hSTAT2 knockin)." (PMID 35462541, 2022). "ZIKV infection of microglia up-regulated STAT1/p-STAT1 and STAT2/p-STAT2 expression." (PMID 35522620, 2022). "In contrast, ZIKV infection in MDMs did not counteract the phosphorylation of STAT1 or STAT2 stimulated by IFN-α treatment." (PMID 33979266, 2021). "Recently, a study showed ADE during ZIKV infection when a murine model lacking STAT2 passively received DENV-immune human sera." (PMID 34684182, 2021). "Given that the expression of NS5 alone did not reduce STAT2 as ZIKV infection did and C7.D29 that exhibited less antagonist activity had similar viral protein levels as C7, it suggests other IFN antagonists exist in the ZIKV infected cells." (PMID 34340648, 2021). "In this study, using biorthogonal system, we found that ZIKV infection suppressed host de novo translation, and reduce the in the expression of STAT2, while ZIKV NS5 did not suppressed host de novo translation." (PMID 34340648, 2021). "This suggests that STAT2 KO hamsters can be used as a non-lethal animal model to study antivirals and vaccine treatment against ZIKV infection." (PMID 30678320, 2019). "As Zika virus does not replicate in wild-type mice, we used Stat2-/- mice which are permissive to Zika virus infection and can display clinical signs of disease." (PMID 30385750, 2018). "Small animal models for ZIKV infection have focused on mice with deficiencies in their IFN response, since the virus has been demonstrated to target human STAT2 proteins to suppress IFN signalling, but not mouse STAT2." (PMID 28672028, 2017). "For example, ZIKV infection in non-pregnant individuals remains asymptomatic despite presumed functional neutralization of type I IFN responsiveness though STAT2 inactivation." (PMID 29145516, 2017). "In ZIKV infection, the NS5 protein could inhibit type I IFN-γ signaling in human cells by targeting the IFN-regulated transcriptional activator STAT2 by proteasome-mediated degradation of STAT2." (PMID 35215836, 2022). "Moreover, passive transfer of anti-DENV IgG did not enhance ZIKV infection in either STAT2—/- knockout or wild-type BALB/c mice." (PMID 34170962, 2021). "Moreover, passive transfer of purified DENV-specific IgG from convalescent human donors did not augment ZIKV infection in STAT2-/- and BALB/c mice." (PMID 34170962, 2021). "Finally, ZIKV NS5 only interacts with human and other non-human primate STAT2 and while wild type mice are immune, IFN deficient mice were susceptible to ZIKV infection, thus showing the importance of this signalling pathway in fighting infection." (PMID 31574966, 2019). "Additionally, ZIKV infection has been suggested to prevent STAT1 and STAT2 phosphorylation." (PMID 29572905, 2018). "Interestingly, while ZIKV infection alone did induce low levels of STAT1 and STAT2 phosphorylation, in most conditions, there was a notable decrease in phosphorylation at MOIs of 1 as compared to MOIs of 0.1, a finding most profound with the African lineage viruses." (PMID 28152048, 2017). "In addition, STAT2 was phosphorylated and the expression of both STAT2 and MxA proteins was seen starting at 24 h after the infection with either one of the viruses indicating that at least some IFN production took place in macrophages in response to ZIKV infection." (PMID 31673117, 2019). "Immune-competent adult mice are resistant to ZIKV infection, in part because ZIKV fails to effectively antagonize Stat2-dependent IFN responses in mice despite ZIKV NS5 protein binding and degrading STAT2 for the immune evasion." (PMID 37191498, 2023). "We further found that ZIKV infection in MDMs did not efficiently suppress type I IFN-mediated antiviral responses and failed to inhibit IFN-α-induced STAT1 and STAT2 phosphorylation." (PMID 33979266, 2021).
ZIKV infection (continued). "Our data further illustrated that ZIKV infection in MDMs did not efficiently suppress type I IFN-mediated antiviral response and failed to antagonize STAT1 and STAT2 phosphorylation induced by IFN-α treatment." (PMID 33979266, 2021). "Upon ZIKV infection at an MOI of 5, hSTAT2 was readily degraded, as evidenced by a reduction in the protein levels of STAT2-HA, whereas the protein levels of mSTAT2 were not affected." (PMID 34340648, 2021). "Wild-type adult mice are resistant to ZIKV infection, primarily due to species-specific differences in type I interferon (IFN) signaling arising from the inability of ZIKV to antagonize human, but not murine, STAT2." (PMID 41525323, 2026). "Thus, to identify the mechanism by which NaAc, PBA, and NaB block the expression of these PRRs, cytokines, IFNs, and ISGs, we measured the activation of NFκB, MAPK (ERK1/2 and p38), STAT1, STAT2, and STAT3 signaling pathways in the presence and absence of these SCFAs following ZIKV infection." (PMID 41358724, 2026). "While in humans, ZIKV inhibits type I IFN signaling by proteasome-mediated degradation of STAT2, it cannot antagonize murine IFN-α/β signaling or effector functions, and wild type adult mice are generally resistant to ZIKV and do not develop the typical clinical manifestations of ZIKV infection." (PMID 39418312, 2024).